CTLA4 (cytotoxic T-lymphocyte associated protein 4)
Diseases named in the same sentence as CTLA4 in open-access papers (continued):
Sharing a sentence is not in itself a finding about the gene and the disease.
type 1 diabetes (continued). "CT60 is a single nucleotide polymorphism within the CTLA-4 locus and the "G" allele is associated with both susceptibility to Type 1 diabetes and low levels of the sCTLA-4 transcript." (PMID 19772653, 2009). "Additionally, the incidence of type 1 diabetes associated with CTLA-4 inhibitors is lower than that of PD-1 inhibitors." (PMID 40264768, 2025). "However, type 1 diabetes, autoimmune thyroiditis, and Addison’s disease have all been linked to genetic risk factors involving the HLA, CTLA4, and PTPN22 genes." (PMID 40951041, 2025). "As previously reported for type 1 diabetes, the cis‐eQTL association of CTLA4 is in the opposite direction to the association with the aggregated trans score; this may be explained by cis‐acting SNPs that alter the splicing of this gene." (PMID 39887658, 2025). "For example, 24-month blockade of CD80 and CD86 via the cytotoxic T-lymphocyte-associated protein 4 (CTLA-4)-immunoglobulin fusion molecule abatacept markedly prolonged beta cell function in new-onset type 1 diabetes and was accompanied by increased numbers of naive T cells." (PMID 33595677, 2021). "Moreover, it has been confirmed by earlier studies the correlation between the c.49A>G polymorphism of the CTLA4 gene and Egyptian, Lebanese, and Iraqi population and type 1 diabetes incidence." (PMID 34342790, 2021). "Moreover, CTLA-4 polymorphisms are associated with occurrence of the multiple autoimmune disorders, including type 1 diabetes." (PMID 33272321, 2020). "Meta-analysis of the CTLA-4 C60T polymorphism on type 1 diabetes risk." (PMID 24465825, 2014). "Meta-analysis of the CTLA-4 G49A polymorphism on type 1 diabetes risk." (PMID 24465825, 2014). "The rate of type 1 diabetes mellitus was higher with anti-PD-1 antibody therapy than with anti-CTLA-4 antibody therapy." (PMID 39902026, 2025). "As one example, CTLA-4-immunoglobulin (CTLA-4–Ig) can alter the functional phenotype of immunogenic dendritic cells in experimental type-1 diabetes by modulating tryptophan catabolism." (PMID 40836971, 2024). "N-glycan branching increased the surface retention time of the T cell activation inhibitory glycoprotein CTLA-4 encoded by the CTLA4 gene, which has been identified as one of the causal candidate genes in type 1 diabetes." (PMID 36907892, 2023). "The CTLA-4 gene has previously been shown to be associated with RA, systemic lupus erythematosus (SLE), multiple sclerosis (MS), type 1 diabetes (T1D), and myasthenia gravis (MG)." (PMID 37497212, 2023). "Regarding ipilimumab, the only anti-CTLA-4 drug included in this study, produced 6 potential signals, in which type 1 diabetes mellitus posed the strongest signal (IC025 = 1.34)." (PMID 35431928, 2022). "It is known that the anti-PD-1 antibody nivolumab and the anti-CTLA-4 antibody ipilimumab can bring about hypopituitarism, thyroid disorder, adrenal cortex dysfunction, and type 1 diabetes mellitus." (PMID 34712202, 2021). "The cytotoxic T-lymphocyte associated protein 4(CTLA-4) gene, which has been mapped to the insulin-dependent diabetes mellitus (IDDM) 12 locus (2q33), encodes a T-cell-specific transmembrane co-receptor." (PMID 28060767, 2017). "Our data also highlight the role of key Treg molecules, CTLA-4, CD25, IL-10 and IL-2, genetically associated with the development of type 1 diabetes, in the response to infection." (PMID 28815218, 2017). "Within the CD4+CD25highCD127low T cell population, 1,25(OH)2D3 or TX527 increased the expression of the Treg-associated molecule cytotoxic T lymphocyte antigen 4 (CTLA-4, CD152) in T cells of control subjects and patients with type 1 diabetes." (PMID 25279717, 2014). "The CTLA4-IgG4 modified imDCs were delivered via the portal vein to the liver of diabetic mice (insulin-dependent diabetes mellitus) before islet xenografting, and mCTLA4-Ig was administered intravenously after xenotransplantation." (PMID 23922766, 2013).
type 1 diabetes (continued). "Distribution of genotype frequencies of CT60 polymorphism of CTLA4 gene and of C1858T polymorphism of PTPN22 gene in type 1 diabetes subjects subdivided according to year of diagnosis." (PMID 23613833, 2013). "LiCTLA-4 may have immunoregulatory functions, as transfection of it into CTLA-4 deficient T cells partially corrects the tendency for hyperresonsiveness, and the liCTLA-4 transcript has been associated with the development of insulin dependent diabetes mellitus in the NOD mouse." (PMID 19772653, 2009). "Type 1 diabetes typically develops after a median of 4.5 courses (95% confidence interval [CI]: 1–17 courses) with anti-PD-1 antibodies and 2.7 courses (95% CI: 1–5 courses) with anti-PD-L1 + anti-CTLA-4)." (PMID 41536580, 2026). "Different mechanisms and targets of anti-PD-1 and anti-CTLA-4 antibodies may partly explain the differences in the incidence of type 1 diabetes mellitus." (PMID 39902026, 2025). "Likewise, abatacept (CTLA4-Ig) have shown promising results in slowing the rate of reduction in beta cell function in individuals with recently diagnosed type 1 diabetes by blocking T-cell co-stimulation." (PMID 37180128, 2023). "Other polymorphisms have been reported to be associated with type 1 diabetes, among those the Cytotoxic T Lymphocyte–Associated Antigen-4 (CTLA-4) and in the Protein Tyrosine Phosphatase Non-receptor type 2 (PTPN22) genes." (PMID 23613833, 2013). "It is likely that components of the pathophysiology and genetic predisposition are conserved across species, and indeed two loci have already been shown to affect type 1 diabetes susceptibility in both species, namely the immunoregulatory MHC HLA class II and CTLA-4 genes." (PMID 15720714, 2005). "Type 1 diabetes mellitus (T1DM) is driven by autoimmune destruction of pancreatic β cells, and genetic susceptibility involves genes related to MHC class II, PTPN22, and CTLA4." (PMID 41511357, 2026). "The risk of type 1 diabetes (T1D) is higher in patients with IPEX (FOXP3, forkhead box P3), WHIM syndrome, autoimmune polyglandular syndrome type 1 (APS type 1 due to AIRE mutation), CTLA4 mutation, deficiency of LRBA, milder forms of ADA deficiency, and STAT1 GOF." (PMID 37102642, 2023). "Type 1 diabetes mellitus is another type of diabetes in which HLA (human lymphocyte antigen), IR1R1 (interleukin-1 receptor type 1), CTLA-4, and VDR are some important genes studied in association with T1DM." (PMID 26587547, 2015). "The aim of the study was to evaluate whether a decreasing trend of high risk HLA, CTLA-4 and PTPN22 genotypes would be present in type 1 diabetes subjects of Continental Italy, a country considered at low incidence of the disease compared to northern European populations." (PMID 23613833, 2013). "APS-2 typically combines PAI with autoimmune thyroid disorders and type 1 diabetes mellitus, and shows a complex inheritance pattern (HLA-DR3/DR4, CTLA-4) similar to isolated autoimmune PAI." (PMID 32938577, 2021). "Due to the limited sample size of subjects, we sub-divided the genotype distribution of CTLA4 and PTPN22 into two groups: 1980–1995 and 1996–2012 according to the year of diagnosis of type 1 diabetes." (PMID 23613833, 2013). "In the non-obese diabetic mouse model, alternative isoforms of CTLA4 (e.g. soluble, B7-independent) have been identified and are suspected to have a role in type 1 diabetes onset through impaired Treg function." (PMID 38720888, 2024). "Our results indicate that IC87114 is not a promising candidate for treatment of type 1 diabetes, even in combination with other drugs such as CTLA4-Ig, but that it leaves the in vivo inflammatory response unchanged." (PMID 26783747, 2016). "Finally, also markers involved in Treg function such as CTLA-4 and FOXP3 were similarly regulated by 1,25(OH)2D3 or TX527 in T cells from patients with type 1 diabetes after additional proinflammatory cytokine stimulation." (PMID 25279717, 2014).
type 1 diabetes (continued). "Only five type 1 diabetes loci with compelling evidence had been identified before the advent of GWA studies: the HLA class II genes on chromosome 6p21; the insulin gene (INS) on 11p15; CTLA4 on 2q33; PTPN22 on 1q13; and, IL2RA/CD25 on 10p15." (PMID 18045485, 2007). "Research design and methods: Three loci(HLA-DQB1, DQA1 and CTLA-4) were analysed in 62 type 1 diabetic patients, 72 firstdegreerelatives and 84 nondiabetic controlsubjects by means of PCR-RFLP." (PMID 11900275, 2002). "Similarly, a case-only gene-gene interaction analysis between C883A and the known type 1 diabetes loci, HLA, INS, CTLA4 and PTPN22, revealed no consistent evidence of an interaction with C883A." (PMID 18045485, 2007).
Immunodeficiency (100 papers, 2004 to 2026). Failure of the immune system to protect the body adequately from infection, due to the absence or insufficiency of some component process or substance. "Monogenic immune disorders, including those associated with CTLA4 mutations, demonstrate distinct immunological and histological profiles, enhancing diagnostic accuracy in cases resistant to standard interventions." (PMID 40724600, 2025). "Costimulatory proteins Cd274 (PD-L1), Ctla4 and Cd86 linked to the immune deficiencies observed in sepsis were upregulated across tissues (12/13 tissues for Cd274, 6/13 tissues for Cd86 and 3/13 tissues for Ctla4)." (PMID 38191855, 2024). "CTLA-4 has immunoregulatory roles in activated T cells and T-reg cells, and splice site variants that can alter CTLA-4 alternative splicing outcomes can result in T cell hyperactivation, immunodeficiency, and a variable degree of immune dysregulation." (PMID 37895245, 2023). "Monoallelic mutations in CTLA4 resulting in inadequate expression of CTLA-4 lead to a disorder characterized by variable immunodeficiency and immune dysregulation." (PMID 36870198, 2023). "CD4+ T-cell cytotoxicity appears to be promoted by primary immune deficiency, particularly CTLA4 deficiency and antagonism." (PMID 37161048, 2023). "Abnormal CTLA-4 isoform ratios have been associated with immune disorders such as Grave’s disease, a T-cell-mediated autoimmune disorder that results in hyperthyroidism." (PMID 37895245, 2023). "Heterozygous mutations in CTLA4 lead to an inborn error of immunity characterized by immune dysregulation and immunodeficiency, known as CTLA-4 insufficiency." (PMID 36405723, 2022). "For example, a CTLA4 eQTL colocalizes with GWAS associations for three immune diseases, where the disease risk alleles decrease gene expression." (PMID 35618845, 2022). "Altered stimulation of cytotoxic T-lymphocyte associated protein 4 (CTLA-4) and programmed cell death protein-1 (PD-1) immune checkpoints also provoke unwanted immunodeficiency in MM patients." (PMID 34759921, 2021). "CTLA4 haploinsufficiency, a relatively common immune disorder, is characterized by autoimmunity, lymphoproliferation in the lung, and immunodeficiency caused by ultimately exhausted immune system." (PMID 33766139, 2021). "A defect in CTLA-4 function, for example by non-sense mutation in the gene encoding CTLA-4, leads to defective TReg function and is accompanied by complex autoimmune disorder and immunodeficiency in humans." (PMID 33123017, 2020). "Activated CD4+ T cells are known to express inhibitory co-receptors, of which cytotoxic T-lymphocyte associate protein 4 (CTLA4) is the best characterized, as mice that lack this co-receptor die of auto-immune disease within the first few weeks of life." (PMID 31212601, 2019). "Moreover, it has been reported that patients with CTLA-4 mutations present a complex dysregulation syndrome characterized by hypogammaglobulinemia, recurrent infections derived from the immunodeficiency and multiple autoimmune diseases." (PMID 34149691, 2021). "CTLA4 deficiency due to heterozygous germline mutations in CTLA4 leading to haploinsufficiency and impaired CTLA4 dimerization or impaired ligand binding, result in an autosomal dominant immune dysregulation syndrome with immunodeficiency." (PMID 31440487, 2019). "However, although aberrant CTLA-4 expression is strongly implicated in immune dysfunction in ESCC, it is likely that multiple other host factors also contribute." (PMID 27050369, 2016). "For example, whether the activated T lymphocytes that cause pathology in patients with CTLA‐4 deficiency are antigenic specific remains unclear, which requires further investigation and understanding of the molecular mechanisms underlying CTLA‐4 and immune disorders." (PMID 38063264, 2023). "High-risk patients showed upregulated PD-1, PD-L1, and CTLA4 (P < 0.001) and higher TIDE scores, indicative of immune dysfunction." (PMID 40535771, 2025).
Immunodeficiency (continued). "The last patient was a 15-year-old girl with severe combined immunodeficiency, specifically a cytotoxic T-lymphocyte antigen 4 (CTLA-4) haplo-insufficiency." (PMID 36844219, 2023). "The prediction of the efficacy of immunotherapy with TICA and TIDE databases proved that the lower SLC7A11 level has a better curative effect of anti-PD-1/PD-L1 and anti-CTLA4 treatment and less probability of immune escape and immune dysfunction." (PMID 37713821, 2023). "Cytotoxic T-lymphocyte antigen-4 (CTLA-4) haploinsufficiency is a T-cell hyperactivation disorder that can manifest with both immunodeficiency and immune dysregulation." (PMID 36636328, 2022). "When we compared the gene expression profiles of the hMSC group compared to the hMSC + DexaTofa group, we discovered enrichments of pathways that were involved in T cell exhaustion, including immunodeficiency, CTLA4, and PD1 signalling pathways." (PMID 36009433, 2022). "Increased expression of IC proteins, such as PD-1, Tim-3, Lymphocyte activation gene 3 (LAG-3), and CTLA-4, resulting in T cell exhaustion is the major reason for T cell immunodeficiency in MM." (PMID 36439426, 2022). "While patients with germline mutations in CTLA-4, LRBA and DEF6 commonly display features such as immune dysregulation and immune deficiency, mice with similar genetic defects are relatively healthy, even upon infectious challenging or aging." (PMID 33996698, 2021). "One major discrepancy between immune disorders in patients with CTLA4 haploinsufficiency and those receiving anti-CTLA4 treatment is the increased susceptibility to infection in CTLA4+/- patients." (PMID 35154081, 2021). "Modulating T-cell activation by targeting the CD28 pathway with CTLA4-Ig has also been a successful approach in treating complex immune diseases." (PMID 33223527, 2020). "Thus, it is likely that these polymorphisms might also influence normal functioning of CTLA-4, give rise to immune dysfunction, jeopardize anti-tumor immune responses, and influence predisposition to malignancies, and this is the reason why we investigated these polymorphisms in this meta-analysis." (PMID 32178688, 2020). "ICOS is a CD28 and CTLA-4 cell-surface receptor family protein, which functions in immunodeficiency biological processes." (PMID 26457008, 2015). "Study reported that high-expressed CTLA4 and CD274 in head and neck squamous cell carcinoma (HNSCC) may cause immune dysfunction in the patients." (PMID 40173324, 2025). "In terms of immune checkpoints, including PD-1 and CTLA4, we discovered that TIDE scores were more accumulated in the high-risk cohort, which implied these patients hold potential immune dysfunction in tumors and could hardlybenefit from immunotherapy." (PMID 39345881, 2024). "On the other hand, RNA-seq data revealed that a variety of immune deficiency markers, such as CD274 (PD-L1), CTLA4, NRP1, and LAGLS9, were increasingly expressed in the high-risk group, which was in line with our previous findings as regards immune suppression of cluster 1 determined by ROGs." (PMID 37252189, 2023). "Similarly, immune deficiency markers, such as CD274 (PD-L1), CTLA4, NRP1, and LAGLS9, were increasingly expressed in the high GRORS tumors." (PMID 37252189, 2023). "Recent studies suggested that CD28 could cooperate with CTLA-4 to mediate T-cell activation, and could be an effective target for applying to many immune diseases." (PMID 36676763, 2023). "Some immune-related pathways and inflammatory pathways were also observed in subtype C4, indicating that the increased expression of PD-1, CTLA4, and PD-L1 might induce immune dysfunction and promote an inflammatory response in subtype C4." (PMID 38025757, 2023). "Aberrant CTLA-4 function leads to uncontrolled T cell responses that clinically manifests as an immune dysregulation syndrome, characterized by autoimmunity and paradoxically by immunodeficiency." (PMID 36405723, 2022).